DNAJC7 (DnaJ heat shock protein family (Hsp40) member C7)
Description:
Acts as a co-chaperone regulating the molecular chaperones HSP70 and HSP90 in folding of steroid receptors, such as the glucocorticoid receptor and the progesterone receptor. Proposed to act as a recycling chaperone by facilitating the return of chaperone substrates to early stages of chaperoning if further folding is required. In vitro, induces ATP-independent dissociation of HSP90 but not of HSP70 from the chaperone-substrate complexes. Recruits NR1I3 to the cytoplasm (By similarity).
Synonyms: TPR2; TTC2; DJ11; DJC7
Tractability: PROTAC: ubiquitination databases record sites on it; its protein half-life has been measured.
Gene: Protein-coding gene on chromosome 17 (41,976,421 to 42,021,376, reverse strand). Ensembl gene ENSG00000168259.
Subcellular location: Cytoplasm; Nucleus; Cytoplasm, cytoskeleton
Subcellular location (Human Protein Atlas): Cytosol; Nucleoplasm
Pathways (Reactome):
Cellular responses to stimuli: Regulation of HSF1-mediated heat shock response
Gene Ontology:
Molecular function: heat shock protein binding; protein binding; ATPase activator activity
Biological process: protein folding; regulation of cellular response to heat
Cellular component: cytoplasm; cytosol; extracellular exosome; membrane; nucleoplasm; nucleus; cytoskeleton
Genetic constraint (gnomAD): Loss-of-function variants: 16 observed, 62.53 expected, observed/expected ratio (o/e) 0.26, 90% interval 0.17 to 0.39. The upper end of that interval is the gene's LOEUF score, 0.39, which puts it in group 1 of 6, group 1 being the genes least tolerant of losing a copy. Missense variants: 397 observed, 590.68 expected, observed/expected ratio (o/e) 0.67, 90% interval 0.62 to 0.73. Synonymous variants: 206 observed, 202.53 expected, observed/expected ratio (o/e) 1.02, 90% interval 0.91 to 1.14.
Gene-disease validity (ClinGen):
ClinGen rates the evidence that DNAJC7 causes each of these diseases.
amyotrophic lateral sclerosis (autosomal dominant): Limited. Amyotrophic lateral sclerosis (ALS) is a neurodegenerative disease characterized by progressive muscular paralysis reflecting degeneration of motor neurons in the primary motor cortex, corticospinal tracts, brainstem and spinal cord.
Homologues: Orthologues: chimpanzee DNAJC7 (99% identical), dog DNAJC7 (98% identical), rabbit DNAJC7 (98% identical), rat Dnajc7 (97% identical), mouse Dnajc7 (97% identical), pig DNAJC7 (94% identical), guinea pig DNAJC7 (93% identical), tropical clawed frog dnajc7 (85% identical), zebrafish dnajc7 (82% identical), Caenorhabditis elegans dnj-8 (11% identical), Drosophila melanogaster l(3)80Fg (9% identical), Caenorhabditis elegans dnj-11 (9% identical), and 6 more. Paralogues in human: DNAJC13 (19% identical), DNAJC2 (12% identical), DNAJC14 (12% identical), DNAJC25 (11% identical), DNAJC17 (11% identical), DNAJC21 (11% identical), DNAJC3 (11% identical), DNAJC1 (11% identical), DNAJC5 (11% identical), DNAJC10 (10% identical), DNAJC16 (10% identical), DNAJC11 (10% identical), and 8 more.
Diseases named in the same sentence as DNAJC7 in open-access papers:
DNAJC7 is named in the same sentence as 16 diseases in open-access papers, as found by Europe PMC text mining. Sharing a sentence is not in itself a finding about the gene and the disease. The quoted sentences say what the papers report.
amyotrophic lateral sclerosis (9 papers, 2020 to 2025). "An additional notable partner is DNAJC7, a chaperone and regulator of protein homeostasis that has recently been identified as a genetic cause for amyotrophic lateral sclerosis." (PMID 34779586, 2021). "Thirdly, loss-of-function mutations in DNAJC7 have been linked to amyotrophic lateral sclerosis." (PMID 40832276, 2025). "DnaJC7 mutations cause dominantly inherited amyotrophic lateral sclerosis (ALS)." (PMID 37387473, 2023). "This screen identified as a strong suppressor of polyQ aggregation the Hsp40 co-chaperone DNAJC7, which has previously been shown to modify aggregation of other disease proteins (tau and TDP-43) and has mutations causative for amyotrophic lateral sclerosis." (PMID 40832276, 2025). "Accumulating studies suggest the involvement of DNAJC7/TPR2 in amyotrophic lateral sclerosis (ALS), likely through binding to natively folded tau and inhibiting tau aggregation." (PMID 34948322, 2021). "DNAJC7 appears to be especially important in motor neurons, supported by its genetic link to amyotrophic lateral sclerosis (ALS) and recent evidence that loss of DNAJC7 in iPSC-derived motor neurons increases susceptibility to proteotoxic stress, in part due to impaired HSF1 signaling." (PMID 40832276, 2025). "DNAJC7, on the other hand, is emerging as a candidate gene for amyotrophic lateral sclerosis (ALS)." (PMID 32093037, 2020).
tauopathy (4 papers, 2021 to 2024). Neurodegenerative disorders involving deposition of abnormal tau protein isoforms (tau proteins) in neurons and glial cells in the brain. "DnaJC7 was shown to coprecipitate with soluble human tau from brain preparations of a tauopathy mouse model and displayed higher binding affinity to natively folded WT relative to mutant tau, suppressing tau aggregation." (PMID 39651147, 2024). "This is consistent with the idea that Hsp70-based coordination of DnaJC7 is central to its activity and is linked to protein aggregation in ALS (which usually doesn’t feature tauopathy) and to regulation of tau." (PMID 36993367, 2023). "We find that DnaJC7 preferentially associates with native conformations of tau isolated from tauopathy mouse brains and CRISPR/Cas9 knockout of DnaJC7 promotes tau aggregation in cells." (PMID 34504072, 2021).
Alzheimer disease (2 papers, 2023). A progressive, neurodegenerative disease characterized by loss of function and death of nerve cells in several areas of the brain leading to loss of cognitive function such as memory and language. "We treated DnaJC7 and DnaJB6 KO cell lines with either recombinant tau fibrils or brain lysates from subjects with Alzheimer’s Disease (AD), Progressive Supranuclear Palsy (PSP), or Corticobasal Degeneration (CBD)." (PMID 36993367, 2023). "We treated DnaJC7 KO and DnaJB6 KO cell lines with either recombinant tau fibrils, DS tau strain cell lysates (DS1, -9, or -10), or brain lysates from subjects with Alzheimer’s disease (AD), progressive supranuclear palsy (PSP), or corticobasal degeneration (CBD)." (PMID 37387473, 2023).
steatosis (2 papers, 2014 to 2021). Increased lipid within the cytoplasm of cells. "Furthermore, other members of the DnaJ protein family have been assigned roles in other liver pathologies, such as steatosis development for DnajC7 and liver cirrhosis for DnajC21." (PMID 34356495, 2021).
liver cancer (1 paper, 2021). An epithelial or non-epithelial malignant neoplasm that arises from the liver. "Several homologs of the Hsp40/DnaJ protein family (DnaJB6, DnaJC1, DnaJC5, DnaJC7, and DnaJC21) have been identified as unfavorable prognostic markers in liver cancer." (PMID 34356495, 2021).
cancer (3 papers, 2021 to 2026). A tumor composed of atypical neoplastic, often pleomorphic cells that invade other tissues. "Promoting USP19-mediated deubiquitination by stabilizing DnaJC7 may offer a novel combination strategy to enhance the efficacy of cisplatin-based cancer therapy." (PMID 42193933, 2026).
infection (2 papers, 2014 to 2025). The state of being infected such as from the introduction of a foreign agent such as serum, vaccine, antigenic substance or organism. "For instance, Dnaja2, Dnajb2, Dnajb12a, Dnajb12b, Dnajb14, Dnajc5ab, Dnajc5gb, Dnajc7, Dnajc16, and Dnajc26 were up-regulated only at 3 days after infection, but not at 14 days after infection; similarly, Dnajc28 was up-regulated only at 14 days after infection, but not at 3 days after infection." (PMID 25542027, 2014).
neurodegenerative disease (2 papers, 2024 to 2025). A disorder of the central nervous system characterized by gradual and progressive loss of neural tissue and neurologic function. "Although we did not specifically identify tau in our native human MN models, these studies flag another potential neurodegenerative disease-relevant function of DNAJC7." (PMID 39651147, 2024).
tumor (1 paper, 2021).
DNAJC7 also shares sentences with these, for which no sentence is quoted: Corticobasal Degeneration (2 papers); progressive supranuclear palsy (2); renal cell carcinoma (2); Autoimmunity (1); frontotemporal dementia (1); liver cirrhosis (1); Parkinson disease (1).